CTNNB1 (catenin beta 1)
Diseases named in the same sentence as CTNNB1 in open-access papers (continued):
Sharing a sentence is not in itself a finding about the gene and the disease.
osteoporosis (21 papers, 2011 to 2025). A condition of reduced bone mass, with decreased cortical thickness and a decrease in the number and size of the trabeculae of cancellous bone (but normal chemical composition), resulting in increased fracture incidence. "These genes were selected as variables to construct a molecular risk model for predicting osteoporosis (risk score = Exp (CTNNB1) × (−1.167227) + Exp (MITF) × (−5.192496) + Exp (TNFSF11) × (12.019122))." (PMID 37893075, 2023). "Based on the osteoclast-regulatory genes (CTNNB1, MITF, and TNFSF11) in the risk model, we used the R package “ConsensusClusterPlus” to cluster the osteoporosis patients." (PMID 37893075, 2023). "In our study, the lowest REL was observed for CTNNB1 and its level decreased inversely to the age of patients with advanced osteoporosis." (PMID 33357212, 2021). "Regarding the group of patients with advanced osteoporosis (Group 4), the expression of CTNNB1 decreased inversely proportional to the age of the patients (R=−0.736, p = 0.0236)." (PMID 33357212, 2021). "Our study aimed to determine how lncRNA DANCR, miR-320a, and CTNNB1 interact with each other and regulate osteogenic differentiation in osteoporosis." (PMID 32778797, 2020). "The expression levels of DANCR and miR-320a in BMSCs derived from osteoporosis patients were upregulated, whereas CTNNB1 expression was downregulated compared with that in healthy controls." (PMID 32778797, 2020). "Consistent with our in vitro experiments, we reported in the present study that DANCR and miR-320a were overexpressed and CTNNB1 was expressed at low levels in our osteoporosis mouse model, leading to the inhibition of the β-catenin signaling pathway." (PMID 32778797, 2020). "Overall, we identified for the first time aberrant expression of DANCR, miR-320a, and CTNNB1 in osteoporosis patients and an OVX animal model." (PMID 32778797, 2020). "Taken together, our findings revealed that DANCR and miR-320a regulated the Wnt/β-catenin signaling pathway during osteogenic differentiation in osteoporosis through CTNNB1 inhibition." (PMID 32778797, 2020). "We observed a relatively high expression of both DANCR and miR-320a and a remarkably lower expression of CTNNB1 in osteoporosis patients." (PMID 32778797, 2020). "To elucidate the biological functions of DANCR, miR-320a, and CTNNB1 in osteoporosis pathogenesis, we first verified and compared their expression levels in BMSCs derived from osteoporosis patients with those in control cells." (PMID 32778797, 2020). "Bone anabolic therapy targeting the Wnt/β-catenin pathway, particularly CTNNB1, represents a novel antiresorptive strategy for osteoporosis treatment." (PMID 32778797, 2020). "The key roles of these three genes in osteoporosis were verified using multivariate logistic regression, with CTNNB1 (OR = 3.501 × 10−7, p = 0.016) and MITF (OR = 2.475 × 10−14, p = 0.002) as protective factors and TNFSF11 (OR = 9.245 × 1022, p = 0.003) as a risk factor." (PMID 37893075, 2023). "CTNNB1 and MITF are protective factors, whereas TNFSF11 is a risk factor for osteoporosis." (PMID 37893075, 2023). "Furthermore, we reported for the first time that DANCR expression was positively correlated with the expression of miR-320a during osteoporosis development and that CTNNB1 expression was negatively correlated with the expression of DANCR and miR-320a." (PMID 32778797, 2020). "Our findings highlight for the first time the role of the interactions between DANCR, miR-320a, and CTNNB1 in osteogenic differentiation and may aid the development of novel therapies for osteoporosis." (PMID 32778797, 2020). "However, we are the first to explore the correlation between DANCR, miR-320a, and CTNNB1 in osteogenic differentiation in osteoporosis." (PMID 32778797, 2020).
osteoporosis (continued). "In this study, we detected three key genes, CTNNB1, MITF, and TNFSF11, using microarray data for osteoporosis." (PMID 37893075, 2023). "TNFSF11 was significantly upregulated (p = 0.001), whereas CTNNB1 (p = 0.001) and MITF (p = 0.017) were significantly downregulated, in the osteoporosis group." (PMID 37893075, 2023). "In conclusion, CTNNB1, MITF, and TNFSF11 were identified as three key genes involved in the occurrence and development of osteoporosis." (PMID 37893075, 2023). "In this study, we isolated BMSCs from osteoporosis patients and found that the molecular levels of DANCR and miR-320a were remarkably higher than those in healthy control cells, whereas CTNNB1 expression was downregulated." (PMID 32778797, 2020). "The results of the current study also showed that CTNNB1 and CAV1 were significantly downregulated in the osteoporosis samples, while SHC1, AKT1 and FLNA were upregulated." (PMID 25815782, 2015). "Differentiation Antagonizing Non-Protein Coding RNA (DANCR) promotes osteoporosis by suppressing osteogenic differentiation through the inhibition of catenin beta 1 (CTNNB1) and the Wnt/β-catenin pathway." (PMID 40873591, 2025). "According to the relevant literature, the effects of AR and CTNNB1 have already been studied well in the related studies, while the effects of PIK3CA still remain unclear in osteoporosis." (PMID 40236832, 2025). "Furthermore, CTSK, CSF1, TNFSF11, CTNNB1, TNFRSF11A, and TNF may be the most promising osteoporosis markers." (PMID 37893075, 2023). "However, the role of the interactions between DANCR, CTNNB1 and miR-320a in osteoporosis has not been investigated or reported." (PMID 32778797, 2020). "However, further efforts are needed to investigate whether and how other molecules interact with DANCR, miR-320a, and CTNNB1 during osteoporosis development, and the important question regarding the reason for DANCR upregulation in osteoporosis patients remains unanswered." (PMID 32778797, 2020).
pilomatricoma (21 papers, 2013 to 2025). "Mutations in CTNNB1 have been identified in a high percentage of pilomatricoma cases, and studies support their pathogenic significance, particularly in tumors associated with syndromic contexts." (PMID 40843798, 2025). "CTNNB1 somatic mutations involving the N-terminal part of the protein have been reported in a high percentage of pilomatrixomas, approximately 75%." (PMID 40843798, 2025). "Several publications have confirmed the presence of CTNNB1 gene mutations, which encode beta-catenin, in both pilomatrixomas and pilomatrix carcinomas." (PMID 40843798, 2025). "Pilomatricoma is a benign neoplasm derived from hair matrix cells associated with β‐catenin gene CTNNB1 mutation." (PMID 39139622, 2024). "In this study, we reviewed literatures involving 30 patients with various genetic syndromes that have been linked to pilomatricoma and found that somatic mutations of the CTNNB1 gene were reported in 67% of patients." (PMID 34956371, 2021). "Some studies have suggested that pilomatrixoma and pilomatrix carcinoma have mutations in the CTNNB1 gene, which encodes beta-catenin." (PMID 34174742, 2021). "We report the first mutation analysis of the CTNNB1 gene in multiple pilomatricomas and in one pilomatrical carcinoma obtained from a single patient with molecular proven DM1." (PMID 32155193, 2020). "Pilomatrixomas are associated with somatic mutations in CTNNB1, which codes for Beta-Catenin, resulting in activation of WNT signaling." (PMID 32265483, 2020). "We analyzed the Catenin beta 1 gene (CTNNB1) for mutations in six samples from four benign pilomatricomas, and in one sample of a pilomatrical carcinoma obtained from the patient." (PMID 32155193, 2020). "Mutations of the catenin-β gene (CTNNB1) have been found in many analyzed non-syndromic pilomatricomas as well as in pilomatricomas associated with constitutive mismatch repair deficiency and in pilomatrical carcinomas." (PMID 32155193, 2020). "CTNNB1-mutations detected in four pilomatricomas (PM) and one pilomatrical carcinoma (PMC) of the described DM1-patient and overview of published mutations in non-syndromic and syndromic PM as well as in PMC." (PMID 32155193, 2020). "In support of this notion, it was shown that distinct pilomatricomas occurring in a single CMMRD patient resulted from different activating CTNNB1 (ß-Catenin gene) mutations." (PMID 27573199, 2017). "Numerous human studies havedemonstrated that mutation of CTNNB1 is a frequent cause of Wnt signaling pathwayactivation in pilomatricoma." (PMID 23596465, 2013). "Both PC and pilomatrixoma involve mutations in the CTNNB1 gene, leading to β-catenin accumulation." (PMID 40765636, 2025). "Furthermore, pilomatricomas and pilomatrix carcinomas frequently harbor CTNNB1 gene mutations, resulting in nuclear β-catenin accumulation, a finding not commonly observed in BCC." (PMID 41356915, 2025). "There are 30% to 100% of pilomatricomas are associated with CTNNB1 gene mutations." (PMID 34956371, 2021). "Various studies have reported that CTNNB1 gene mutations in pilomatricoma and pilomatrix carcinoma." (PMID 34956371, 2021). "The presence of ATM in BASC could hint to a link between the enhanced mutation rate of CTNNB1 in the analyzed pilomatricomas and the detected ATM germline mutation." (PMID 32155193, 2020). "To determine if routine cytological specimens can be successfully used to perform additional investigation and support or confirm the diagnosis in three cases of pilomatrixoma, we performed molecular analysis and immunohistochemistry to search for CTNNB1 mutation and β-catenin, respectively." (PMID 32908727, 2020). "CTNNB1 mutations have been reported in a high percentage of pilomatrixomas." (PMID 32908727, 2020). "Mutations of the catenin-β gene (CTNNB1) could be demonstrated in most non-syndromic pilomatricomas." (PMID 32155193, 2020).
pilomatricoma (continued). "As multiple pilomatricomas with CTNNB1 mutations have been described in patients with PMS2 germline mutations, we analyzed the stability of microsatellite DNAs BAT25, BAT26, D2S123, D5S354 and D17S250 in two pilomatricomas of the patient (G34dup, T41I) and in the pilomatrical carcinoma." (PMID 32155193, 2020). "Alterations of the DNA mismatch repair proteins might therefore still be responsible for the observed enhanced mutation rate of the CTNNB1 gene in the pilomatricomas of the DM1 patient." (PMID 32155193, 2020). "Therefore, mutation of the CTNNB1 most likely represents the tumor driving oncogenic event in pilomatricoma." (PMID 32155193, 2020). "Both pilomatrixoma and PC share CTNNB1 gene mutations, supporting a “two-hit hypothesis”: an initial mutation results in β-catenin accumulation leading to pilomatrixoma, and a second mutation affects tumor suppressor or proto-oncogenes, resulting in malignant transformation." (PMID 40765636, 2025). "This frequency is greater than all the other tumors, suggested that the alteration of CTNNB1 pathway is a relevant molecular finding in pilomatrixoma." (PMID 40843798, 2025). "Indeed, both the components were positive for cytoplasmic and sometimes nuclear expression, and knowing that β-catenin in a pilomatricoma and pilomatrical carcinoma was able to be induced by mutations in exon 3 of CTNNB1, it could be that these mutations may be contributory to pilomatrical tumors." (PMID 39051324, 2024). "CTNNB1 expression was strongly upregulated as it has been described before in non-syndromic pilomatricoma." (PMID 32155193, 2020). "Pilomatricomas resulting from Ctnnb1 activation in Lgr5-expressing stem cells were surrounded by an increased density of vimentin+ fibroblasts, while fibroblast density in the rest of the skin was unaffected." (PMID 26771241, 2016). "On the other hand, the CTNNB1 oncogenic variant is a non-germline mutation, so it is expressed only in the pilomatricoma cells and not in all the cells of the organism." (PMID 40843798, 2025). "This overview shows that mutations of codon 33 and 37 of CTNNB1 are represented at about the same frequency in non-syndromic pilomatricoma." (PMID 32155193, 2020). "CTNNB1 immunohistochemistry was performed on one pilomatricoma." (PMID 32155193, 2020). "Pilomatricoma has been attributed to CTNNB1 mutations in both nonsyndromic and syndromic cases." (PMID 34956371, 2021). "This might indicate that lack of microsatellite instability in pilomatricomas may not rule out a causative role of DNA mismatch repair in the enhanced mutation rate of the CTNNB1 gene." (PMID 32155193, 2020). "The WNT/APC/β-catenin pathway regulates hair follicle development, hair follicle cycling, and hair growth and β-catenin is strongly expressed in the proliferating matrix cells of pilomatricoma, both in catenin-β mutated tumors and in pilomatricomas without a CTNNB1 mutation." (PMID 32155193, 2020).
thyroid cancer (21 papers, 2017 to 2025). "Activation of the Wnt/β-catenin signaling is often caused by activating mutations of CTNNB1 (which encodes β-catenin) in thyroid cancer, particularly in poorly differentiated thyroid cancer (PDTC) and anaplastic thyroid carcinoma (ATC)." (PMID 28740507, 2017). "Indeed, mutations of Wnt pathway mediators, such as CTNNB1 (catenin beta 1) and Axin1, also appear to be common in advanced thyroid carcinomas." (PMID 33986723, 2020). "Also, CTNNB1 (β-catenin) is frequently mutated and is constitutively active in poorly differentiated thyroid cancers and ATC29,42–44." (PMID 30760700, 2019). "In the present study, we investigated the tumorigenicity of thyroid cancer cells derived from BRAFV600E PTC mice following Ctnnb1 ablation (BVE-Ctnnb1null)." (PMID 37483610, 2023). "In this study, we investigated the tumorigenicity of thyroid cancer cells derived from BrafV600E -induced PTC mice with wild-type Ctnnb1 (BVE-Ctnnb1wt) and deleted Ctnnb1 (BVE-Ctnnb1null)." (PMID 37483610, 2023). "The important role of β-catenin gene (CTNNB1) in thyroid cancer pathogenesis has been established by several studies." (PMID 30760700, 2019). "The ‘liver neoplasms’ CTD over-representation could be attributed to cell cycle-related pathway enrichment and corresponding genes (cell cycle: PDS5A, ORC6, RAD21, ZBTB17; Thyroid cancer: CTNNB1, RET) identified from our CRIPSR screens." (PMID 41446233, 2025). "This might be different for dedicator of cytokinesis 9-antisense RNA2 (DOCK9-AS2) that sponges microRNA-1972 (miR-1972), leading to the upregulation of catenin β1 (CTNNB1) in thyroid cancer." (PMID 35883472, 2022). "Besides, CCND1 and CTNNB1 were also reported to function as oncogenes in thyroid cancer." (PMID 33363164, 2020). "Interestingly, we identified that the DPP4/CTNNB1/MET gene signature was overexpressed in PTCa, which, according to our analysis, is associated with immuno-invasive phenotypes, cancer progression, metastasis, resistance, and unfavorable clinical outcomes of thyroid cancer cohorts." (PMID 35205190, 2022). "Mutations in genes encoding members of the WNT signaling pathway—i.e., Catenin Beta 1 (CTNNB1), AXIN1 and Adenomatous Polyposis Coli (APC)—are hallmarks of less differentiated thyroid carcinomas, in particular, ATCs." (PMID 31540307, 2019). "Next, the expression levels of CTNNB1, ACTB, and CCND1 in thyroid carcinoma were also determined." (PMID 33363164, 2020). "Only three miRNA–gene pairs (miR-876-3p-CTNNB1, miR-876-3p-ACTB, and miR-876-3p-CCND1) revealed a statistically negative expression relationship in thyroid carcinoma." (PMID 33363164, 2020).
Familial adenomatous polyposis (19 papers, 2011 to 2026). Familial adenomatous polyposis (FAP) is characterized by the development of hundreds to thousands of adenomas in the rectum and colon during the second decade of life. "Known risk factors for DF include APC and beta-catenin (CTNNB1) gene mutations, as in familial adenomatous polyposis, along with prior surgery, trauma, pregnancy, and oral contraceptive use." (PMID 41181483, 2025). "Both sporadic DT and familial adenomatous polyposis (FAP)-associated DT are linked to constitutive activation of the Wnt signaling pathway with mutations in the β-catenin oncogene CTNNB1 or the tumor suppressor gene APC, respectively." (PMID 36068332, 2022). "This abnormal activation can be attributed to either a germline mutation that leads to the loss of function of the tumor suppressor gene APC in the context of familial adenomatous polyposis (FAP), or somatic mutations occurring in the β-catenin gene (CTNNB1)." (PMID 39410565, 2024). "DTF tumours do occur in the context of familial adenomatous polyposis (FAP), but the majority of DTF tumours are sporadic and characterised by mutations in the β-catenin (CTNNB1) gene." (PMID 35158976, 2022). "Somatic activating mutations in the CTNNB1 gene (Wnt/β-catenin pathway) are the predominant driver in sporadic DTs, whereas germline mutations in the APC (adenomatous polyposis coli) gene underline FAP (familial adenomatous polyposis) and Gardner syndrome." (PMID 41227209, 2025). "All four tumors in patients with familial adenomatous polyposis (FAP) analyzed in this study, were assigned to the CTNNB1 wild type group (n = 23/204; 11.3%)." (PMID 32099073, 2020).